BIN3 (bridging integrator 3)
Description:
Involved in cytokinesis and septation where it has a role in the localization of F-actin.
Tractability: PROTAC: ubiquitination databases record sites on it; its protein half-life has been measured.
Gene: Protein-coding gene on chromosome 8 (22,620,418 to 22,669,148, reverse strand). Ensembl gene ENSG00000147439.
Subcellular location: Cytoplasm, cytoskeleton
Gene Ontology:
Molecular function: protein binding; cytoskeletal anchor activity; lipid binding
Biological process: intracellular protein localization; unidimensional cell growth; actin cortical patch localization; actin filament organization; cytoskeleton-dependent cytokinesis; endocytosis; plasma membrane tubulation; developmental growth
Cellular component: actin cytoskeleton; cytoplasm; cytoskeleton
Genetic constraint (gnomAD): Loss-of-function variants: 41 observed, 36.69 expected, observed/expected ratio (o/e) 1.12, 90% interval 0.87 to 1.45. The upper end of that interval is the gene's LOEUF score, 1.45, which puts it in group 5 of 6, group 1 being the genes least tolerant of losing a copy. Missense variants: 361 observed, 326.98 expected, observed/expected ratio (o/e) 1.1, 90% interval 1.01 to 1.21. Synonymous variants: 145 observed, 125.25 expected, observed/expected ratio (o/e) 1.16, 90% interval 1.01 to 1.33.
Homologues: Orthologues: chimpanzee BIN3 (100% identical), macaque BIN3 (98% identical), guinea pig BIN3 (97% identical), dog BIN3 (96% identical), rabbit BIN3 (95% identical), mouse Bin3 (94% identical), zebrafish bin3 (82% identical), rat Bin3 (77% identical), pig BIN3 (75% identical), tropical clawed frog bin3 (74% identical), Caenorhabditis elegans amph-1 (19% identical). Paralogues in human: BIN2 (25% identical), AMPH (24% identical), BIN1 (24% identical).
Diseases named in the same sentence as BIN3 in open-access papers:
BIN3 is named in the same sentence as 18 diseases in open-access papers, as found by Europe PMC text mining. Sharing a sentence is not in itself a finding about the gene and the disease. The quoted sentences say what the papers report.
anxiety disorder (1 paper, 2021). A category of psychiatric disorders which are characterized by anxious feelings or fear often accompanied by physical symptoms associated with anxiety. "BIN3, which encodes a protein involved in cytokinesis is associated with anxiety disorder." (PMID 33935957, 2021).
colorectal cancer (1 paper, 2023). A primary or metastatic malignant neoplasm that affects the colon or rectum. "It was previously reported that low BIN3 expression was an independent predictor of unfavorable survival in patients with primary colorectal cancer Thus, it was supposed that BIN3 might also be a tumor inhibitor." (PMID 36475339, 2023).
dementia (1 paper, 2021). Loss of intellectual abilities interfering with an individual's social and occupational functions. "SNP rs2280194 in BIN3 and rs10253857 in an intergenic region near SNX13 are associated with a family history of dementia." (PMID 33935957, 2021).
esophagus carcinoma (1 paper, 2023). "Nevertheless, little is known about the role and clinical value of BIN3 in esophagus carcinoma (ESCA)." (PMID 36475339, 2023).
Parkinson disease (1 paper, 2025). A progressive degenerative disorder of the central nervous system characterized by loss of dopamine producing neurons in the substantia nigra and the presence of Lewy bodies in the substantia nigra and locus coeruleus. "This revealed potential regulatory SVs near enhancers at genes like BIN3 that colocalized with GTEx expression of nearby risk genes and Parkinson’s disease GWAS." (PMID 41282933, 2025). "Colocalization with Alzheimer’s and Parkinson’s disease GWAS implicated SVs at multiple loci, including TMEM106B, BIN3, and NBEAL1." (PMID 41282933, 2025). "An ADRC methylation signal colocalized with the BIN3 Parkinson’s disease locus, where an intronic Alu insertion (chr8:22625890; 329 bp) acts as a methylation QTL for a nearby variable methylation segment (PP4 = 0.89) and is included in the fine-mapped credible set." (PMID 41282933, 2025).
tumor (2 papers, 2023 to 2025). "BIN3 functions as a tumor-suppressor role in ESCA, which is significantly associated with the immune infiltration of ESCA." (PMID 36475339, 2023). "Next, we evaluated the association between BIN3 expression and tumor immune infiltrate levels using TIMER2 databases." (PMID 36475339, 2023). "Third, the tumor suppressor role of BIN3 in ESCA should be investigated by much more in vitro experiments and in vivo studies." (PMID 36475339, 2023). "BIN3 expression was observed to be decreased in ESCA tumor tissues compared to normal tissues from TCGA and GTEx database." (PMID 36475339, 2023). "Tumor immune infiltration analysis indicated that there was a strong correlation between levels of immune cell infiltration and the expression of BIN3." (PMID 36475339, 2023). "We also found that BIN3 was closely related to the tumor immune microenvironment by different algorithms." (PMID 36475339, 2023). "Consistent with the bioinformatics analysis in ESCA tumor tissues, BIN3 mRNA level was significantly decreased in ESCA cell lines (TE-1, KYSE30 and KYSE150) compared to normal human esophagus epithelial cell line Het-1A." (PMID 36475339, 2023). "Above all, our results suggest that BIN3 may play a tumor-suppressor role in ESCA and serve as a potential biomarker in the prognosis of ESCA." (PMID 36475339, 2023). "Based on the bioinformatics data and experiments, our findings suggest that BIN3 may act as a tumor-suppressor role in ESCA and might be a potential prognostic factor for ESCA patients." (PMID 36475339, 2023). "However, only BIN3 was downregulated in ESCA tumor tissues compared to normal tissues, suggesting a tumor suppressor role in tumorigenesis." (PMID 36475339, 2023).
infection (1 paper, 2021). The state of being infected such as from the introduction of a foreign agent such as serum, vaccine, antigenic substance or organism. "In the recovered phage bins, we also identified genes related to bacterial defence systems, with 13 genes from Bin1, Bin2, and Bin3 being involved in RM, DISARM, bacteriophage exclusion system, abortive infection, Septu, or Zorya." (PMID 34479645, 2021).
BIN3 also shares sentences with these, for which no sentence is quoted: cancer (3 papers); Alzheimer disease (1); autism (1); cardiomyopathy (1); coronary heart disease (1); deafness dystonia syndrome (1); esophageal squamous cell carcinoma (1); heart failure (1); microcephaly (1); neurodevelopmental disorder (1); spastic hemiplegia (1).